GLI1 (GLI family zinc finger 1)
Diseases named in the same sentence as GLI1 in open-access papers (continued):
Sharing a sentence is not in itself a finding about the gene and the disease.
oral squamous cell carcinoma (5 papers, 2017 to 2024). "For example, higher GLI1 expression is associated with more advanced (and metastatic) tumors and low expression of GLI1 confers longer survival in patients with oral squamous cell carcinoma (SCC)." (PMID 28562331, 2017). "Oral squamous cell carcinoma (OSCC) invades surrounding tissues by upregulating matrix metalloproteinases (MMPs) -2 and −9, which causes over-expression of the Hedgehog signaling proteins Shh and Gli-1 and degradation of the extracellular matrix, thereby creating a “highway” for tumor invasion." (PMID 29157266, 2017). "In oral squamous cell carcinoma, SHH and GLI1 are both found in the stromal compartment and could be the source of the ligand for both paracrine and autocrine activation in the tumor cells." (PMID 38731849, 2024).
prostate tumor (5 papers, 2013 to 2024). "As such, the niche role of stromal AR in Gli1-lineage cells to promote prostate tumor initiation and progression has been assessed using newly generated mouse models and human PCa datasets and samples." (PMID 39369165, 2024). "GLI1 and pGLI1 were expressed in the nucleus and cytoplasm in both prostate tumor and stromal tissue." (PMID 38370352, 2024). "There was a significant correlation between Sonidegib exposure and a decrease in GLI1 expression in both plasma (P =0.0009) and prostate tumor tissue (P=0.0009)." (PMID 29262631, 2017). "Similarly, the expression of Shh and Gli1 was also observed in epithelial and stromal cells in human prostate tumor tissues, confirming the paracrine regulations between tumor epithelia and stroma." (PMID 39369165, 2024). "Interestingly, SHH-GLI1 pathway components often show enhanced expression in tumor versus normal prostatic epithelia, and suppressing GLI1 expression in primary prostate tumor cell cultures inhibits cell proliferation." (PMID 38751776, 2024).
serous ovarian cancer (5 papers, 2011 to 2025). "In addition, multivariate analysis showed that nuclear Gli1 was independently associated to poor survival in advanced serous ovarian cancer patients (HR = 2.2, 95%CI 1.0–5.1, p = 0.04)." (PMID 23555905, 2013). "The Gli1 mRNA expression data from the microdissected stroma of human serous ovarian cancer confirmed that the Hh pathway is active in human ovarian stroma, and demonstrated that elevated Gli1 mRNA levels are associated with shorter survival." (PMID 23303278, 2013). "To this end we first investigated immunohistochemically the expression of Gli1 protein in normal ovarian surface epithelium and in advanced serous ovarian cancers and correlated its expression with clinicopathological parameters and patient outcomes." (PMID 23555905, 2013). "Overall, our clinical data support the role of Gli1 as a prognostic marker in advanced serous ovarian cancer and as a possible therapeutic target in this disease." (PMID 23555905, 2013). "In the present study we investigated the prognostic role of Gli1 in a homogenous population of advanced serous ovarian cancers showing that patients whose tumors express nuclear Gli1 staining (>10%) experience a shorter OS compared to negative cases (≤10%)." (PMID 23555905, 2013). "In conclusion, our study highlights that evaluation of Gli1 expression in advanced serous ovarian cancer may provide clinicians with important clues to prognosis, a finding needing confirmation in large-scale prospective clinical trials." (PMID 23555905, 2013). "Though the stromal compartment in this model is murine, the Gli1 mRNA expression data from the microdissected stroma of human serous ovarian cancer confirms that the Hh pathway is active in human ovarian stroma, and that the degree of activation may be of prognostic value." (PMID 22140510, 2011). "This analysis revealed an enrichment of SHH pathway genes, including GLI1, GLI2, HHIP, PTCH1, and PTCH2, in SSTs as compared to high-grade serous ovarian cancers and other sex cord-stromal tumors." (PMID 31896750, 2020).
atherosclerosis (4 papers, 2020 to 2025). A disease characterized by the build-up of fatty material and calcium deposition in the arterial wall resulting in partial or complete occlusion of the arterial lumen. "To elucidate the role of these adventitial progenitor cells in atherosclerosis, we utilized the AdvSca1-SM cell lineage tracing mouse model we previously developed and validated (Gli1-CreERT/Rosa26-YFP)." (PMID 37991018, 2023). "The team also found that Gli1+cells can migrate to the media and intima plaques and when calcification occurs in atherosclerosis, Gli1+ cells differentiate into osteoblasts." (PMID 35224067, 2022). "Therefore, the findings presented in this study suggest that modulating miR-214-3p-Sufu-GLI1 axis could be a potential therapeutic tool for vascular diseases such as atherosclerosis and post-angioplasty restenosis." (PMID 33143723, 2020). "Adventitial stem cells (ASCs), identified by Gli1 expression, have been proposed as key contributors to the vascular smooth muscle cell (SMC) population during atherosclerosis development." (PMID 41332333, 2025). "During atherosclerosis in Apoe intima; these are MSC-like cells expressing Gli1 marker." (PMID 35224067, 2022).
brain glioma (4 papers, 2017 to 2020). A malignant glioma that involves the brain. "GLIs, and especially GLI1 in human brain gliomas, play important roles in cell-cycle and apoptosis regulation." (PMID 33218150, 2020). "It has been reported that the inhibition of GLI1 induces cell-cycle arrest and enhances apoptosis in brain glioma cell lines." (PMID 30770723, 2019). "As nuclear staining of Gli1 is a reliable marker of HH pathway activity in brain glioma, the percentage of Gli1 nuclear staining was used to divide the 48 surgically resected GBM samples into Gli1-positive or Gli1-negative groups." (PMID 29225516, 2017). "Furthermore, dysregulation of Gli-1 may result in aberrant activation of the SHH pathway during initiation of brain glioma." (PMID 29867331, 2018).
cerebellar tumor (4 papers, 2016 to 2023). "The GLI1 mRNA is highly edited, which induces an increase in the capacity of GLI1 to activate transcription by adenosine deamination in the normal cerebellum, but the process is obviously decreased in cell lines originating from cerebellar tumors." (PMID 31379511, 2019). "Here, primary GNPs expressing GLI1/GFP were injected and resulted in cerebellar tumor formation." (PMID 37608807, 2023).
gallbladder cancer (4 papers, 2018 to 2024). "Promote GLI1 nuclear localization and binding to target gene promoter, promote gallbladder cancer metastasis and macrophage recruitment." (PMID 39483334, 2024). "In gallbladder cancer, ASPP2 deficiency was found to mediate tumor invasion and metastasis through the aPKC-ι/GLI1 pathway." (PMID 34572373, 2021). "Consequently, GLI1 contributes to the progression of multiple cancer types, including colorectal cancer, liver cancer, stomach cancer, pancreatic cancer, lung cancer, gallbladder cancer, prostate cancer, ovarian cancer, and glioblastoma." (PMID 39483334, 2024). "Similarly, ASPP2 depletion in gallbladder cancer cell lines was shown to enhance the expression and binding of aPKC-ι with GLI1." (PMID 34572373, 2021). "High GLI1 expression is correlated with worse prognosis of gallbladder cancer." (PMID 31979397, 2020). "The expressions of SHH, PTCH, and GLI1 are upregulated in gallbladder cancer." (PMID 31979397, 2020).
inflammatory bowel disease (4 papers, 2010 to 2020). A spectrum of small and large bowel inflammatory diseases of unknown etiology. "The Sufu-GLI1 signal axis has been reported to play a critical role in the intestinal inflammatory response, and decreased GLI1 activity predisposes to a heightened myeloid response to inflammatory stimuli in inflammatory bowel diseases." (PMID 33143723, 2020). "Moreover, a common single nucleotide polymorphism (SNP) in human GLI1, which reduces protein activity by around 50%, is associated, in both homozygous and heterozygous states, with increased risk of inflammatory bowel disease." (PMID 26288817, 2015).
leiomyosarcoma (4 papers, 2020 to 2025). An uncommon, aggressive malignant smooth muscle neoplasm, usually occurring in post-menopausal women. "GANT61 caused significant regression of the leiomyosarcoma growth and decreased expression of Gli1 and its target genes: BMP4 and c-MYC." (PMID 37815662, 2023). "Inhibition of DNA methyltransferase by 5aza-dC was found to reduce PTCH1 DNA methylation, accompanied by decreased SMO and GLI1 expression and inhibition of GLI1 and GLI2 nuclear translocation in leiomyosarcoma cell lines." (PMID 34572373, 2021). "Recently, we demonstrated that uterine leiomyosarcoma cells exhibited an upregulation of SMO and GLI1 members concomitantly with an increase in nuclear translocation of GLI-1 and 2 compared to uterine smooth muscle cells." (PMID 33179013, 2020).
lung squamous cell carcinoma (4 papers, 2017 to 2020). "Similarly, reverse correlation was observed between GLI1 and E-cadherin in lung squamous cell carcinoma." (PMID 31036836, 2019).
malignant pleural mesothelioma (4 papers, 2014 to 2021). A malignant neoplasm that arises from mesothelial cells in the pleura and shows a diffuse growth pattern. "A hampered Survivin expression following SMO inhibition has further been described for malignant pleural mesothelioma, an effect rescued by overexpression of GLI1, suggesting an involvement of GLI1 transcription factor." (PMID 30142876, 2018). "In this study, we show that CK2α is over-expressed and a positive regulator of Hegdehog/Gli1 signaling in human malignant pleural mesothelioma." (PMID 25422081, 2014). "Our results suggest that CK2α is over-expressed and positively regulates Hh/Gli1 signaling in human malignant pleura mesothelioma." (PMID 25422081, 2014).
metastatic melanoma (4 papers, 2017 to 2026). A melanoma that has spread from its primary site to another anatomic site. "Binding of GLI1 to the SPP1 gene promoter was reported in metastatic melanoma cells indicating it could be a general feature of malignant cells." (PMID 28030801, 2017). "In line with this, a 2.5-fold increase in GLI1 expression was observed in metastatic melanoma, although this difference did not achieve statistical significance." (PMID 41596411, 2026).
myeloid leukemia (4 papers, 2019 to 2023). A clonal proliferation of myeloid cells and their precursors in the bone marrow, peripheral blood, and spleen. "The Smo/Gli-1 pathway plays critical roles in embryogenesis and developmental processes, and its activity is essential for chemoresistance and maintenance of LSCs in myeloid leukemia." (PMID 33743723, 2021). "The expression of Hh signaling proteins, including SMO and GLI1 in radiation-resistance myeloid leukemia cells, are higher than that observed in radiation-sensitive myeloid leukemia cells, suggesting that Hh pathway activation is related to radiotherapy resistance." (PMID 30987263, 2019).
osteoarthritis (4 papers, 2015 to 2023). A noninflammatory degenerative joint disease occurring chiefly in older persons, characterized by degeneration of the articular cartilage, hypertrophy of bone at the margins and changes in the synovial membrane. "Strikingly, intra-articular injection of Gli1+ meniscal cells or an Hh agonist right after injury accelerated the bridging of the interrupted ends and attenuated signs of osteoarthritis." (PMID 34085927, 2021).
pancreatic adenocarcinoma (4 papers, 2017 to 2020). "Furthermore, pharmacologic blockade of TGF-β signaling leads to a reduction of GLI1 expression in cyclopamine-resistant pancreatic adenocarcinoma." (PMID 29456503, 2017).
periodontitis (4 papers, 2021 to 2025). An acute or chronic inflammatory process that affects the tissues that surround and support the teeth. "Interestingly, periodontitis compromised dental pulp stem cells secrete EVs carrying miR-378 to promote local angiogenesis to activate the Hedgehog/Gli1 signaling pathway." (PMID 36524049, 2022). "CUL3 degrades Gli1 and then down-regulates Nrf2 in periodontitis." (PMID 34193016, 2021). "SHH is reported to potentially serve as a new therapeutic target for periodontitis and periodontal regeneration, the expression of which along with that of Gli1 in PDLSCs was examined in this study and was found to have an obvious increase after Pg-LPS stimulation." (PMID 34193016, 2021).
polydactyly (4 papers, 2013 to 2023). A disease characterized by the presence of polydactyly, including syndromic and non-syndromic forms. "In a second case (Case 2), we found a heterozygous likely pathogenic variant in the GLI1 gene that has been associated with two types of polydactyly (phenotype present in our patient) and reported as autosomal recessive (source: OMIM database)." (PMID 36675175, 2023).
renal carcinoma (4 papers, 2015 to 2023). A carcinoma arising from the epithelium of the renal parenchyma or the renal pelvis. "For instance, in renal carcinoma cells, treatment with LDE225 showed reduced cell proliferation, concomitant with lower GLI1 and GLI2 expression." (PMID 33396427, 2020). "Interestingly, no significant change was observed in the expression of HES1, GLI1 and NANOG, whereas the expression of CTNNB1 was markedly increased, suggesting that CTNNB1 may be involved in increased renal cancer stem-like phenotype caused by the down-expression of PIK3R1." (PMID 25757764, 2015). "Therefore, we decided to investigate the immunoreactivity of the two major SHH pathway proteins, SHH and GLI1, as well as the expression of one of their important targets - VEGFA, in this type of renal cancer." (PMID 37964226, 2023).
skin cancer (4 papers, 2016 to 2025). "In addition, it was notable that only BCCs were found to express GLI among the malignant skin tumors, suggesting GLI1 as a candidate diagnostic marker in differentiating BCC from other skin malignancies." (PMID 31756206, 2019). "In this study, we investigated the expression profile of six HH pathway molecules (GLI1, GLI2, PTCH1, PTCH2, SMO, and SHH) in BCCs and other benign and malignant skin tumors by real-time PCR and immunohistochemistry." (PMID 31756206, 2019).
thyroid tumor (4 papers, 2017 to 2022). A benign or malignant neoplasm affecting the thyroid gland. "In thyroid tumors, the treatment downregulated the GLI1 protein expression and reduced the tumor volume." (PMID 34642915, 2022). "Our recent study showed that the inhibitors of the Shh pathway such as cyclopamine (CP), a Smothened (SMO) inhibitor, and GANT61, a Gli1 inhibitor, have modest inhibitory effects on thyroid tumor cell proliferation and tumor growth." (PMID 33966040, 2021). "mRNAs and proteins of Shh, Ptch, Smo, and Gli1 were detected in three thyroid tumor cell lines (KAT-18, SW1736, and WRO82)." (PMID 29163356, 2017).
adenoma (3 papers, 2016 to 2022). A neoplasm arising from the epithelium. "GLI1 expression levels were significantly elevated in ACTH-, GH- and PRL-expressing adenomas (p = 0.026; p = 0.035; p = 0.0059, respectively) whereas null cell adenomas and FSH-expressing tumors showed similar GLI1 expression levels compared to normal adenopituitary lobes." (PMID 27109116, 2016). "Since hormone producing cells of the adenohypophysis as well as ACTH-, GH- and PRL-immunopositive adenomas express SHH and its target GLI1, we furthermore propose that excess HH signaling is involved in the development/maintenance of hormone-producing pituitary adenomas." (PMID 27109116, 2016). "Normal thyroids were all negative for Gli1, whereas tumors were positive, with a higher proportion of positive cells in ATC than in adenoma and FTC." (PMID 29435119, 2018).
anaplastic thyroid cancer (3 papers, 2018 to 2021). "GANT61, a Gli1-specific inhibitor, induced LC3 lipidation in two anaplastic thyroid cancer cell lines, SW1736 and KAT-18 cells, in a dose- and time-dependent manner." (PMID 33966040, 2021). "Here we report that inhibition of the Shh pathway by Gli1 siRNA or by cyclopamine and GANT61 induced autophagy in SW1736 and KAT-18 cells, two anaplastic thyroid cancer cell lines; whereas Gli1 overexpression suppressed autophagy." (PMID 33966040, 2021). "Here we report that inhibition of the Shh pathway by Gli1 siRNA or by cyclopamine and GANT61 reduced BMI1 and SOX2 expression in SW1736 and KAT-18 cells, two anaplastic thyroid cancer cell lines." (PMID 33499351, 2021).
astrocytoma (3 papers, 2010 to 2020). "With regard to the molecular mechanism, we found that upregulation of NUSAP1 promoted the translocation of GLI1 from the cytoplasm to the nucleus and upregulated the downstream genes of the HH pathway in astrocytoma cells." (PMID 28899410, 2017). "With regard to its molecular mechanism, upregulation of NUSAP1 in astrocytoma cells promoted the nuclear translocation of GLI family zinc finger 1 (GLI1) and upregulated the downstream genes of the Hedgehog pathway." (PMID 28899410, 2017). "Our data indicated that NUSAP1 promoted GLI1 translocation to the nucleus from the cytoplasm and subsequently led to activation of the HH signaling pathway in astrocytoma cells." (PMID 28899410, 2017). "Our findings indicated that NUSAP1 activated HH pathway by promoting GLI1 transport to the nucleus form cytoplasm in astrocytoma cell." (PMID 28899410, 2017). "Subsequent to GLI1 silencing, we observed an increase in PAX6 expression in the transfected astrocytoma cell line U87MG." (PMID 21059263, 2010). "On the contrary, we observed significant correlation of GLI1 expression with downstream target genes PTCH1 (p = 0.07), Cyclin D2 (p = 0.006), Plakoglobin (p = 0.02), PAX6 (p = 0.006) and NKX.2.2 (p = 0.0001) in astrocytoma cell lines." (PMID 21059263, 2010). "Our observations on the expression of GLI1, Cyclin D2, and PTCH1 in astrocytoma cell lines as well as tumor samples revealed a significant proportion of samples showing low or null levels of Cyclin D2 and PTCH1, even in the presence of high GLI1 expression." (PMID 21059263, 2010).
chordoma (3 papers, 2014 to 2024). Chordomas are rare malignant tumors arising from embryonic remnants of the notochord in axial skeleton. "Due to the high Shh and GLI1 expression levels in all investigated chordoma samples, the study suggests a possible autocrine ligand-dependent activation of the canonical HH signaling cascade." (PMID 30769952, 2019). "Due to the high expression of Shh and GLI1 in all investigated chordoma samples, the present results suggest a ligand-dependent SHH signaling cascade activation in cranial and spinal chordomas, as well as their relapse." (PMID 30769952, 2019). "Overall, 14 (100%) cranial chordomas from eight patients were immunohistochemically assayed for expression levels of Shh and GLI1." (PMID 30769952, 2019). "Due to the high levels of SHH and GLI-1 expression in all investigated chordoma samples, the study suggests a possible autocrine ligand-dependent activation of the canonical HH signaling cascade." (PMID 30769952, 2019). "Cranial chordomas were examined for the expression of Ptch1 and GLI1 by in situ hybridization." (PMID 30769952, 2019). "RNA-Seq and NanoString analyses confirmed the upregulation of PTCH1 and GLI1, further indicating SHH pathway activation in chordomas." (PMID 39568072, 2024). "These methods demonstrated overexpression of SHH and its downstream effectors, particularly GLI1, indicating active SHH signalling in chordomas." (PMID 39568072, 2024). "On the other hand, negative responses for PTCH1 and GLI1 were detected in the first spinal chordoma recurrences." (PMID 30769952, 2019).